AR (androgen receptor)
Diseases named in the same sentence as AR in open-access papers (continued):
Sharing a sentence is not in itself a finding about the gene and the disease.
prostate carcinoma (continued). "Different prostate cancer therapies consequently focus on blocking the androgen receptor pathway." (PMID 33671614, 2021). "In addition, the knock-out of FASN gene expression by siRNA process reduced androgen-induced prostate cancer cell proliferation (left) and transcriptional activity of the AR (right) in VCaP prostate cancer cells." (PMID 34944692, 2021). "Hypoxia has been reported to induce AR signaling in hormone-sensitive LNCaP prostate cancer cells, but it remains unknown whether CRPC cells also utilize this signaling pathway and whether it confers a survival advantage in hypoxia." (PMID 33671134, 2021). "The end result is AR stimulation of oncogene expression which promotes growth of prostate cancer." (PMID 34045511, 2021). "In sharp contrast, androgen receptor-positive prostate cancer cells cannot induce TCIPA." (PMID 34322381, 2021). "MiR-let-7c is another miRNA that decreases expression and activity of AR in prostate cancer cells." (PMID 34831421, 2021). "Because the development and progression of prostate cancer (PCa) depends on AR signaling, inhibition of AR signaling by androgen deprivation therapy (ADT) (e.g., luteinizing hormone-agonist/antagonist with or without casodex) is the mainstay of treatment for advanced castration-sensitive PCa (CSPC)." (PMID 34071114, 2021). "Notably, the androgen receptor (AR) is essential for both normal development of prostate and prostate cancer progression." (PMID 33219721, 2021). "Prostate cancer growth is primarily driven by AR signaling, which could be effectively depleted with androgen-competing chemicals." (PMID 33801338, 2021). "Other studies, in the context of prostate cancer, have identified AR-regulated miRNAs and lncRNAs." (PMID 34831421, 2021). "Moreover, bicalutamide-mediated AR blocking has resulted in the prompt release of this miRNA into the media of cultured prostate cancer cells." (PMID 34831421, 2021). "The role of the androgen receptor in prostate cancer has been extensively studied, but recent data suggest that androgen receptor signaling may also be important in breast cancer, glioblastoma, and additional tumor types." (PMID 34778082, 2021). "ETS-related gene (ERG) upregulates the downstream mediator transcription factor of the Wnt/β-catenin signaling pathway named Lymphoid enhancer-binding factor 1 (LEF1), which in turn enhances the androgen receptor expression and activity, leading to prostate cancer in an androgen-independent manner." (PMID 35201496, 2021). "Androgen receptor is highly expressed in invasive breast cancer and prostate cancer cells." (PMID 34659545, 2021). "PRNCR1 was reported to have high expression in aggressive prostate cancer and was reported to enhance both ligand-dependent and ligand-independent AR-mediated transcriptional activity by directly binding to the region of 549-623 amino acids of AR and therefore promotes prostate cancer growth." (PMID 34946977, 2021). "Therefore, we proposed that p38 MAPK inhibition would decrease cell proliferation in prostate cancer cells that are dependent on AR signaling for survival." (PMID 33671134, 2021). "Genome-wide analysis of prostate cancer risk SNPs and somatic SNVs demonstrated that they converge and enrich at the binding sites of other master transcription factors besides FOXA1, including AR, HOXB13 and SOX9." (PMID 32946061, 2021). "The results of transactivation experiments showed that darolutamide and its two optical isomers and major metabolite-keto-darolutamide showed strong competitive antagonism against AR wild type, which have differences in inhibiting AR activity in prostate cancer VCaP, LAPC-4, and LN CaP cell lines." (PMID 34976824, 2021). "Here, we investigated whether IL-6-mediated AR activation can regulate IRE1α expression in prostate cancer cells." (PMID 34295814, 2021). "A recent study showed that androgen-mediated AR activation could induce IRE1α expression in prostate cancer cells." (PMID 34295814, 2021).
prostate carcinoma (continued). "Androgen receptor (AR) is known to positively regulate the expression Fgf2 in prostate cancer." (PMID 34957471, 2021). "While still needing further hit-to-lead optimization, the prototype AR NTD inhibitor VPC-220010 could provide avenue to overcome common CRPC resistance mechanisms by decreasing prostate cancer cell growth through an AR-directed mechanism of action." (PMID 34298700, 2021). "However, little work has been done to understand the molecular mechanism underlying the modulation function of PRPF6 on AR action and the role of PRPF6 in prostate cancer." (PMID 33390843, 2021). "For example, some androgen receptor inhibitors (e.g., apalutamide, enzalutamide, and darolutamide) can delay metastases in high-risk nonmetastatic castration-resistant prostate cancer." (PMID 34834295, 2021). "On the other hand, expression of HOXC8 is inversely correlated with the progression and metastasis of pancreatic ductal adenocarcinoma; HOXC8 inhibited androgen receptor signaling in human prostate cancer cells by inhibiting SRC-3 recruitment to direct androgen target genes." (PMID 35111675, 2021). "AR inhibitors have been developed for treatment of prostate cancer and could be repurposed for COVID-1945." (PMID 35602214, 2021). "It is possible that the “MAPK/PI3K-Akt switch” function of PSMA could help the prostate cancer cells to try to survive castration when AR activation is suppressed." (PMID 34067046, 2021). "Several studies highlighted the key role played by the androgen-receptor (AR) axis in prostate cancer pathogenesis and subsequent progression, explaining the rationale of the use of androgen-deprivation therapy (ADT) as upfront treatment in metastatic prostate malignancy." (PMID 33557050, 2021). "In prostate cancer, pARS210/213 is responsible for AR protein stability and nuclear translocation." (PMID 34681618, 2021). "Malignancies arising from these organs are frequently driven by abnormal activity of the receptors of these sex hormones: indeed, >90% of prostate cancers (PC) are driven by the androgen receptor (AR) and ~70% of breast cancers (BC) are driven by the estrogen receptor-α (ER)." (PMID 34209750, 2021). "AR plays a role in the development and progression of prostate cancer (PCa)." (PMID 34864817, 2021). "Moreover, histone deacetylase inhibitors have been evaluated in castration-resistant prostate cancer (CRPC) or chemotherapy-resistant prostate cancer due to their effects on the expression of the androgen receptor gene." (PMID 33672425, 2021). "Besides, a study in prostate cancer identified CCNB1 as a bona fide AR target gene in prostate stromal cells." (PMID 34797837, 2021). "Several studies have previously discussed the critical role of TMPRSS2 in the context of SARS-Co-V-2 infection, including a recent review by our team wherein we have discussed the association between TMPRSS2, AR, and SARS-Co-V2 in the context of prostate cancer." (PMID 33915795, 2021). "Therefore, it is important to identify and characterize co-regulators that play a key role in mediating these complexes, are crucial for driving AR transcriptional activity and growth, and are upregulated in prostate cancer." (PMID 33513133, 2021). "Interestingly, in prostate cancer cells a direct interaction between the AR and the GLI proteins has been found." (PMID 34290270, 2021). "Another report described that the orphan receptor, probable G-protein coupled 158 (GPR158) receptor promotes prostatic cell proliferation (in human prostate cancer cells) independently of androgen receptor function and stimulates androgen receptors and prostate specific antigen expression." (PMID 34066915, 2021). "In two prostate cancer cell lines, LNCaP (high androgen receptor activity, low invasiveness) and PC3 (low androgen receptor activity, highly metastatic), both peptides, Ang II and relaxin 2, induced proliferation, however, greater changes were observed in androgen-dependent cell line." (PMID 33673178, 2021).
prostate carcinoma (continued). "Intriguingly, reconstituted expression of E‐cadherin in E‐cadherin‐negative prostate cancer cells caused the redistribution of β‐catenin to the cell membrane, and consequent reduction of AR‐dependent activity." (PMID 33085215, 2021). "Conversely, decreased AR expression and AR-responsive gene signaling is often observed in PTEN-deficient prostate cancer cells and, in this setting, inhibition of PI3K/AKT signaling results in the reactivation of AR through a reciprocal feedback loop between AR and AKT." (PMID 34439133, 2021). "Between primary prostate cancers of different patients, AR cistromes are highly variable." (PMID 33576154, 2021). "AR has an essential role in the pathogenesis of human cancers, particularly prostate cancer." (PMID 34831421, 2021). "Selective inhibition on androgen receptor (AR)-negative prostate cancer cell growth; induction of apoptosis with associated increased expressions of proapoptotic proteins: death receptor-5, Bim, Puma and downregulation of XIAP and survivin expressions." (PMID 34630112, 2021). "However, several studies have shown that various signaling pathways are regulated by androgen stimulation at earlier time points (5 to 60 min), and that this rapid AR signaling contributes to prostate cancer cell proliferation." (PMID 34944692, 2021). "For example, in prostate cancer, Kallikrein-related peptidase 3 eRNA (KLK3e), an eRNA produced by KLK3’s upstream enhancers, can selectively enhance the androgen receptor (AR)-dependent gene expression, resulting in a positive effect on prostate cancer cell proliferation." (PMID 33996902, 2021). "Androgen receptor (AR) is the main carcinogen in the development of prostate cancer." (PMID 34540687, 2021). "Moreover, in a study using human LNCaP human prostate cancer xenografts in mice, it was reported that the growth inhibition of tumors was accompanied by the downregulation of the androgen receptor (AR) and a decrease in prostate-specific antigen (PSA) levels." (PMID 33498364, 2021). "Androgen receptor (AR) is the principal molecule in prostate cancer (PCa) etiology and therapy." (PMID 33932081, 2021). "In addition to this, resveratrol also mimics the polyubiquitination of proteasomes of androgen receptor splice variant (ARV7) in the 22RV1 cell line, showing its anti-prostate cancer potential." (PMID 33807174, 2021). "AR gene mutations also lead to several pathological situations such as androgen insensitivity syndrome (AIS), spinal and bulbar muscular atrophy (SBMA), and prostate cancer." (PMID 34276780, 2021). "Treatment of prostate cancer confronts resistance to androgen receptor (AR)-targeted therapies." (PMID 34127815, 2021). "The role of testosterone/AR in prostate cancer and breast cancer has been well studied." (PMID 33613770, 2021). "In addition to prostate cancer, the effects of miRNAs on AR have been investigated in other cancer types." (PMID 34831421, 2021). "Of note, we also found zero overlap of core AR regions with metastasis‐specific AR sites further showing that our core AR sites that were also identified in healthy tissue and primary prostate cancers are separate biologically from metastasis‐specific AR sites." (PMID 33576154, 2021). "In conclusions, we have identified a new AR/AR-V7 degrader named ARVib and showed that ARVib effectively degrades AR/AR-V7 protein through the ubiquitin-proteasome pathway mediated by the HSP70/STUB1 complex and attenuates AR/AR-V7 downstream target gene expression in prostate cancer cells." (PMID 34272475, 2021). "Notably, the most striking changes between the two groups were found again in the AR/ERG co-bound gene set in primary prostate cancers 3,6." (PMID 33531470, 2021). "AR mediates androgen effects via hormone-receptor binding in normal tissues in both male and female although androgen-independent AR activation is a common finding in castration-resistant prostate cancers." (PMID 34094902, 2021).
prostate carcinoma (continued). "Recent studies have suggested the AR regulates a network of key DNA repair genes, providing a potential mechanism by which androgen deprivation may synergise with radiotherapy for prostate cancer." (PMID 34367984, 2021). "Furthermore, according to the data by Dehghannasiri and colleagues, up to 10% of prostate cancer fusions involve lncRNAs as the other partner, making it likely that more AR-driven lncRNA fusions will be discovered." (PMID 33634124, 2021). "However, advanced prostate cancers are likely to be AR-independent and easily to recur, and therefore lack effective therapeutic strategies." (PMID 34476012, 2021). "Mechanistically, SENP1 overexpression was associated with the increased expression of several transcription factors essential for the development and progression of prostate cancer, such as androgen receptor (AR) and HIF-1α, which is critical for neoangiogenesis." (PMID 33923236, 2021). "Histone deacetylases (HDACs) are overexpressed in AR− and AR+ prostate cancers, and, therefore, HDACs might be an important drug target for prostate cancers." (PMID 34681244, 2021). "The bidirectional coupling between AR signaling and EMT offer a possible mechanistic link associating the progression of cells towards a partial or full EMT and gain of therapy resistance in prostate cancer." (PMID 33652914, 2021). "Additionally, a few in vitro studies that were performed on human-derived prostate cancer cell lines suggested that flavonoids can also target the androgen-dependent signaling pathway by AR activation." (PMID 33799482, 2021). "The findings may have important implications for the treatment of prostate cancer patients in an HN or early CRPC because it may prevent the dedifferentiation of cancer cells as an escape mechanism to AR-directed therapeutic interventions." (PMID 34857732, 2021). "Because GV1001, as a new GnRHR ligand and a YAP1 inhibitor, represents a potential therapeutic for prostate cancer without causing cancer cell migration and metastasis by AR depletion." (PMID 34743733, 2021). "Moreover, miR-185-mediated inhibition of AR has suppressed the proliferation of prostate cancer cells and enhanced their apoptosis." (PMID 34831421, 2021). "Aside from PARP7 being established as a direct androgen receptor (AR) target gene, very little is known about PARP7 in prostate cancer (PCa) where AR signaling plays a major role, and we set out to explore the interplay between AR signaling and PARP7 in this context." (PMID 33572475, 2021). "Bombesin increases the growth of human prostate cancer cells and activates AR." (PMID 34067046, 2021). "In the last two decades, the therapeutic scenario of metastatic castration-resistant prostate cancer has been enriched by the use of chemotherapy and androgen receptor signaling inhibitors (ARSI) and, more recently, by immunotherapy and poly(ADP–ribose) polymerase (PARP) inhibitors." (PMID 33557050, 2021). "Thus, our findings provide helpful insights into prostate cancer progression generally and the relationship between intracellular factors and AR signaling cascades, specifically." (PMID 34680521, 2021). "In prostate cancer, AR is critical for initiation and development." (PMID 34822423, 2021). "This could explain the suppressive effect of metformin on the function of the androgen receptor in prostate cancer cells." (PMID 34211461, 2021). "Nevertheless, partial ARPI- resistant CRPC may eventually develop NEPC due to AR- independent mechanisms in prostate cancer." (PMID 34956090, 2021). "We know that FOXA1 has been reported to help shape AR signaling and drives growth and survival of prostate cancer cells, Which may be a potential explanation for the differences in prognosis among White, Black, and Asian PCa patients." (PMID 34148031, 2021).
prostate carcinoma (continued). "There are many known targets for prostate cancer treatment, including androgen receptor (AR) axis, but drug resistance and metastasis eventually develop in advanced disease, suggesting the necessity to better understand the resistance mechanisms and consider multi-target medical treatment." (PMID 34611139, 2021). "Concerning prostate cancer, topoisomerases cooperate with androgen receptor signaling." (PMID 34782700, 2021). "Prostatic cancer may develop AR deprivation resistance for several reasons including AR amplification." (PMID 33534004, 2021). "Under low androgen condition, prostate cancer cells increase AR expression." (PMID 34572923, 2021). "It was found that, in a cellular model of prostate cancer, only full-length AR could phase separate on its own, where its splice variant lacking LBD, AR-v7, did not undergo LLPS." (PMID 34884563, 2021). "Similarly, androgen receptor (AR) signaling represents the dominant route supporting prostate cancer cells proliferation." (PMID 34576327, 2021). "The androgen receptor (AR) plays a central role in prostate cancer (PCa) development, and androgen deprivation therapy (ADT, medical or surgical castration) to suppress AR activity is the standard treatment for metastatic PCa, but tumors invariably recur (castration-resistant prostate cancer, CRPC)." (PMID 34911936, 2021). "The results suggest that the cell apoptosis induced by proxalutamide may be correlated with the impairment of AR expression or AR signaling, as with other anti-prostate cancer drugs." (PMID 34948018, 2021). "In addition, KDM8 overexpression induces activation of AR transcriptional activity and promotes cell growth in prostate cancer in vitro and in vivo." (PMID 34220955, 2021). "Targeting the androgen receptor (AR)/PGD feedback loop in prostate cancer." (PMID 34382934, 2021). "Combination therapy with these AR suppressive mechanisms may be used as an adjunct to ADT to abrogate endocrine resistance in prostate cancer." (PMID 35582006, 2021). "AR is the key signaling pathway in both normal prostate and prostate cancer growth." (PMID 33637115, 2021). "In soft agar assays, the growth of AR-positive prostate cancer cells overexpressing KLF5 was suppressed by androgen withdrawal or enzalutamide treatment, and cell cycle activity was lowest in LTL-331 tumors when KLF5 expression and basal cell activity were highest." (PMID 34737261, 2021). "Therefore, the GR can bypass AR inhibition in prostate cancer cells by reactivating the downstream AR signaling output." (PMID 33671614, 2021). "To further confirm our results, we investigated known AR signaling genes more closely and as well as genes encoding for proteins that are most commonly associated with AR biology in prostate cancer (FOXA1, AR, and HOXB13), and found them virtually identical across all samples." (PMID 33576154, 2021). "AR gene aberration and mutation might therefore interfere with and functionally impair HR and PARP pathways, which are upregulated in prostate cancer cells." (PMID 34298770, 2021). "Androgen receptor (AR) signaling mainly controls prostate cancer (PCa) growth." (PMID 34298665, 2021). "In prostate cancer, AR remains the best‐characterised driver of prostate cancer progression." (PMID 34434533, 2021). "Accordingly, we have considered the possibility that the survival of CK2 in prostate cancer may be mediated by the maintenance and promotion of androgen receptor and NF-κB p65 expression." (PMID 33997273, 2021). "Furthermore, half of the “prostate cancer” pathway DEGsSD are well described in the PCa literature (AR, CDKN1A, CTNNB1, EGFR, KLK2, NKX3-1, PDGFRA, SRD5A2), confirming that this is a pivotal pathway to specifically target clinical questions on canine PCa." (PMID 34768937, 2021). "Early studies indicated that ASC-J9®, an androgen receptor (AR) degradation enhancer, could suppress the prostate cancer (PCa) progression." (PMID 33390173, 2021).